BMP7 (bone morphogenetic protein 7)
Diseases named in the same sentence as BMP7 in open-access papers (continued):
Sharing a sentence is not in itself a finding about the gene and the disease.
uveal melanoma (4 papers, 2013 to 2025). A melanoma derived from melanocytes of the uveal tract. "One study explored the relationship between BMP-7 expression and the tumorigenicity and malignant behavior of uveal melanoma, as well as the effect of BMP-7 overexpression on tumor growth in vivo." (PMID 40696418, 2025). "On the contrary, decreased BMP7 expression can disrupt melanocyte homeostasis in normal melanocytes and inhibit tumor growth in human uveal melanomas, whereas upregulation of BMP7 correlates with tumor progression." (PMID 31316551, 2019).
asthma (3 papers, 2014 to 2022). "Increased levels of BMP4 and BMP7 have been shown to inhibit the differentiation of human lung fibroblasts into myofibroblasts during asthma remodeling and block the production of extracellular matrix proteins by these cells." (PMID 35770504, 2022). "Our data suggest that influencing the balance between the antifibrotic and profibrotic TGF-β/Smad signalling pathways using BMP7-mimetic compounds presents an unprecedented opportunity to inhibit subepithelial fibrosis during airway remodelling in asthma." (PMID 33020537, 2020). "Despite the different variables that can influence the effect of in vivo treatment with BMP-7, our work is the first description of the anti-fibrotic role of BMP-7 in an allergic setting, such as asthma." (PMID 24781156, 2014). "Type-I collagen around bronchi, α-SMA, mucus secretion, TGF- β1 and BMP-7 gene expression were all increased in asthma." (PMID 24781156, 2014). "When we compared the expression of these molecules in acute and chronic protocols of asthma, we found that the gene expression for BMP-7 is increased in the acute compared with the chronic group, but the expression of TGF-β1 was similar in both groups." (PMID 24781156, 2014). "We propose that the TGF-β1/BMP-7 ratio could be used as a marker of disease severity in asthma, as has been proposed for renal chronic fibrosis." (PMID 24781156, 2014). "In the present study we investigated the effect of the anti-fibrotic molecule BMP-7 in asthma." (PMID 24781156, 2014). "We speculate that in asthma, an increase in BMP-7 expression occurs after the first exposures to the antigen, aiming to protect the lung from the allergic injury." (PMID 24781156, 2014). "Moreover, it suggests the possibility of interfering with the fibrotic process in asthma by intranasal instillation of BMP-7." (PMID 24781156, 2014). "Additionally, a recent report showed that in a mouse model of asthma, the balance between TGF-β1 and BMP7 could be used to predict the intensity of lung fibrosis." (PMID 33020537, 2020).
breast tumors (3 papers, 2013 to 2022). "BMP7 expression in patients with primary breast tumors exclusively developing bone metastases is significantly lower than in primary breast tumors developing exclusively visceral (lung and/or liver) metastases." (PMID 26237148, 2013).
cardiac hypertrophy (3 papers, 2015 to 2025). "The bone morphogenetic protein-7 (BMP-7) has been demonstrated to counteract the pro-fibrotic effects of TGF-β by attenuating cardiac hypertrophy and collagen deposition in patients and mice models of left-sided pressure overload." (PMID 40298654, 2025). "For example, we observed deregulation of chamber-specific factors (e.g. Myh7, Bmp7, Anf, Acta1, Egr1 and Fos) that are also upregulated in adult cardiac hypertrophy and/or heart failure." (PMID 25803368, 2015). "Notably, BMP-7 has been shown to reduce cardiac hypertrophy and fibrosis, while also restoring heart function." (PMID 41471266, 2025).
cardiomyopathy (3 papers, 2017 to 2021). A disease of the heart muscle or myocardium proper. "BMP7 activates infiltrating monocytes into anti-inflammatory M2 macrophages, which inhibits apoptosis and fibrosis in prediabetic cardiomyopathy." (PMID 28769795, 2017). "In the current study, we investigated the therapeutic potential of a cardiac-targeted bone morphogenetic protein 7 (BMP7) gene therapy, administered once diastolic dysfunction was present, mimicking the timeframe in which clinical management of the cardiomyopathy would likely be desired." (PMID 34690762, 2021).
cleft palate (3 papers, 2012 to 2015). Cleft palate is a fissure type embryopathy that affects the soft and hard palate to varying degrees. "BMP7 deficient mice display cleft palate, and it has also been involved in the pathogenesis of human craniofacial malformations including NSCL/P." (PMID 25662552, 2015). "As expected, mice deficient for Irf6, Msx1, Tgf-β3, or Bmp7 partially or completely mimic the cleft palate phenotype of humans with mutations or polymorphisms in these genes." (PMID 23055981, 2012). "This question was addressed by studying Bmp7-deficient mice, which develop cleft palate due to a delay in shelf elevation." (PMID 23055981, 2012). "Clearly additional molecular or cellular processes are regulated by BMP7, and without their characterization it will be difficult to establish a causal link between BMP7 deficiency and the development of specific malformations such as micrognathia and cleft palate." (PMID 23516636, 2013). "Similarly, Bmp7-deficient mouse embryos show numerous orofacial abnormalities, including absence of eyes, discontinuity of the cranial and acoustic bones, micrognathia, missing or malformed/misplaced teeth, and cleft palate with 100% penetrance." (PMID 23516636, 2013). "To understand the etiology of cleft palate linked to the BMP signaling pathway, we studied palatogenesis in Bmp7-deficient mouse embryos." (PMID 23516636, 2013). "However, the etiology of these orofacial manifestations is not yet investigated, and therefore in the present study we focused on the causes of the cleft palate phenotype due to absence of Bmp7." (PMID 23516636, 2013). "Conditional ablation of Bmp7 with Keratin14-Cre or Wnt1-Cre revealed that neither epithelial nor neural crest-specific loss of Bmp7 alone could recapitulate the cleft palate phenotype." (PMID 23516636, 2013).
coloboma (3 papers, 2010 to 2021). An abnormality in which a part of a structure in one or both eyes is missing. "We identified novel variants in genes such as TFAP2A and CHD7, and previously reported variants in RARB and BMP7, indicating that mutations in known coloboma‐associated genes account for only 4.5% of the coloboma cohort analyzed." (PMID 31816153, 2020). "Family 2: A heterozygous variant predicted to cause a Leu198Phe change in BMP7 cosegregated with the coloboma phenotype in mother and daughter (NM_001719.2, NP_001710.1)." (PMID 31816153, 2020). "The correct patterning of the optic fissure is dependent on the actions of Bmp7 and Shh and mutations in Pax2 and Vax1 lead to a deficiency in the closure of the optic fissure, a condition known as coloboma." (PMID 20386732, 2010). "In particular, bmp-7 expression was elevated at the presumptive fusional edges of the optic fissure, suggestive of a role in fissure closure, and consistent with the presence of coloboma in individuals with BMP-7 mutations." (PMID 34685584, 2021). "Of the 38 known coloboma‐associated genes, the analysis identified novel variants in two genes, CHD7, TFAP2A, and previously reported variants in RARB and BMP7, in a total of four unrelated families." (PMID 31816153, 2020).
diabetic retinopathy (3 papers, 2023 to 2024). "have pinpointed six significant genes (CD44, CDC42, TIMP1, BMP7, RHOC, FLT1) as crucial for diabetic retinopathy through advanced bioinformatics analysis coupled with in vivo validation." (PMID 38605967, 2024).
esophageal squamous cell carcinoma (3 papers, 2023 to 2025). Esophageal squamous cell carcinoma (ESCC) is a type of esophageal carcinoma (EC) that can affect any part of the esophagus, but is usually located in the upper or middle third.
follicular lymphoma (3 papers, 2012 to 2017). Follicular lymphoma is a form of non-Hodgkin lymphoma characterized by a proliferation of B cells whose nodular structure of follicular architecture is preserved. "We and others have demonstrated expression of BMP7 mRNA in GC B cells from human tonsils and in malignant B cells from follicular lymphoma (FL) and mantle cell lymphoma (MCL) patients." (PMID 28489883, 2017). "Furthermore, malignant B cells from tumor samples of three out of three Follicular lymphoma (FL) patients expressed high levels of BMP7, whereas it was undetectable in the malignant B cells from two Diffuse large B-cell lymphoma (DLBCL) patients." (PMID 23049692, 2012). "BMP7 was demonstrated to be methylated both in human DLBCL and follicular lymphoma indicating its physiological relevance." (PMID 28912427, 2017).
intervertebral disc degeneration (3 papers, 2015 to 2023). "Combination therapy using BMP-7 and FoxC2 may be beneficial to the treatment of intervertebral disc degeneration." (PMID 26824865, 2016).
long bone fracture (3 papers, 2011 to 2025). "A total of fifteen SNPs within four genes of the Bone Morphogenetic Protein (BMP) pathway (BMP-2, BMP-7, NOGGIN and SMAD6) were examined, in 109 randomly selected patients with long bone fractures as a result of motor vehicle accident, fall or direct blow." (PMID 21310029, 2011). "However, in another prospective randomized controlled study involving 120 cases, the clinical and radiographic efficacy of using recombinant human bone morphogenetic protein-7 (rhBMP-7) combined with PRP for treating long bone fracture nonunions was found to be inferior to that of the rhBMP-7 group." (PMID 40433239, 2025). "Novel and sensitive assays for the quantification of BMP7-aAB and BMP2-aAB were established and used to analyze serum samples from healthy controls (n = 100 men, n = 100 women) and patients with long bone fracture (n = 265) treated or not with rhBMP7." (PMID 27617228, 2016).
lung adenocarcinoma (3 papers, 2016 to 2024). A carcinoma that arises from the lung and is characterized by the presence of malignant glandular epithelial cells. "As the p value of BMP7 is close to significance in the multivariate model, we searched in The Gene Expression Omnibus (GEO) database for a second cohort of lung adenocarcinoma patients to have at least 100 patients." (PMID 32973129, 2020). "In vitro cell studies have shown that downregulating BMP-7 expression can significantly inhibit the invasiveness of lung adenocarcinoma SPC-A1 cells, while upregulating BMP-7 notably promotes the migration ability of A549 cells." (PMID 38571500, 2024). "In TCGA lung adenocarcinoma cohort, we found BMP7 significant in univariate Cox analysis but not significant in multivariate Cox model including BMP7 and Stage." (PMID 32973129, 2020).
mantle cell lymphoma (3 papers, 2013 to 2023). Mantle cell lymphoma is a rare form of malignant non-Hodgkin lymphoma affecting B lymphocytes in the lymph nodes in a region called the ``mantle zone''. "BMP7 expression was also found to correlate with the development of secondary drug resistance in mantle cell lymphoma." (PMID 37688374, 2023). "Variations in gene expression after treatment point out BMP7 as a key gene involved in secondary resistance in mantle cell lymphoma." (PMID 24069261, 2013). "Our findings suggested that BMP-7 could be a gene involved in secondary drug resistance in these mantle cell lymphomas." (PMID 24069261, 2013).
metabolic syndrome (3 papers, 2013 to 2023). A cluster of metabolic risk factors for CARDIOVASCULAR DISEASES and TYPE 2 DIABETES MELLITUS. "Since increased plasma TG levels are an independent risk factor for cardiovascular disease in both men and women BMP7 might thus be an interesting treatment modality to manage cardiovascular disease through attenuating dyslipidemia via targeting BAT." (PMID 24066098, 2013).
Myocardial fibrosis (3 papers, 2019 to 2022). "BMP7 has been proved to inhibit cell apoptosis, myocardial fibrosis and anti calcification, and can improve the cardiac function of patients." (PMID 35346191, 2022). "BMP-7 treatment significantly attenuated myocardial fibrosis, reduced the infarct size, and improved cardiac function." (PMID 31979268, 2020). "Mainly, exogenous administration of recombinant BMP7 decreased TGFβ1 signaling in different areas of the left ventricle, as well as the myocardial fibrosis level and infarct size." (PMID 31547567, 2019). "BMP7 was proven to limit myocardial fibrosis via attenuating TGFβ1 signaling also in the rat acute myocardial infarction model (AMI)." (PMID 31547567, 2019). "In addition, this study also reported that BMP-7 treatment inhibited myocardial fibrosis by attenuating TGF-β signaling and its downstream effectors Smad-2 and Smad-3." (PMID 31979268, 2020). "Recently, a study suggested that BMP7 may counteract myocardial fibrosis through limiting the TGFβ1/SMAD3 dependent down-regulation of E-cadherin and up-regulation of collagen I and αSMA in myocardial fibroblasts." (PMID 31547567, 2019).
ovarian carcinoma (3 papers, 2016 to 2023). A malignant neoplasm originating from the surface ovarian epithelium. "The current study aimed to assess BMP7 protein expression in a large cohort of ovarian carcinoma patient tumour samples to establish its associations with different clinical endpoints." (PMID 37688374, 2023). "High expression of BMP7 mRNA was also significantly associated with poor disease specific survival in the TCGA PanCancer Atlas ovarian cancer cohort further strengthening the importance of BMP7 in ovarian cancer." (PMID 37688374, 2023). "High BMP7 expression is associated with aggressive ovarian cancer clinicopathological variables including advanced FIGO stage, high grade, residual disease and poor overall survival." (PMID 37688374, 2023). "This is in line with the BMP7 protein expression data suggesting that high expression of BMP7 is associated with poor survival in ovarian cancer patients." (PMID 37688374, 2023). "BMP7 mRNA expression had a 259.84‐fold increase in at 4 h and a 351.79‐fold increase at 24 h, suggesting a higher expression in more aggressive ovarian carcinomas than in early‐stage disease." (PMID 37688374, 2023). "EMT related gene expression profiling demonstrated the ovarian cancer cell line PEO4 had a 260‐352‐fold overexpression of BMP7 gene with inhibition of calpains by calpeptin treatment compared to the vehicle treated cells." (PMID 37688374, 2023). "The current study built upon such data by assessing BMP7 protein expression in a large cohort of ovarian carcinoma patient samples by standard immunohistochemistry approaches, using full face tumour sections and tissue microarrays." (PMID 37688374, 2023). "In this regard, the association between BMP7 expression and residual disease also points towards the potential prognostic significance of BMP7 expression in ovarian cancer." (PMID 37688374, 2023). "The study highlights the potential of BMP7 as a prognostic tool and as a potential novel target for ovarian cancer therapies to limit disease progression." (PMID 37688374, 2023). "In vitro data obtained previously indicated the potential significance of BMP7 expression in ovarian cancer." (PMID 37688374, 2023). "This association between BMP7 expression and high tumour grade suggests BMP7 plays a role in the development and progression of ovarian cancer by regulating cell proliferation." (PMID 37688374, 2023). "Following on from such previous findings, this current study reports protein expression of BMP7 in a large cohort of human ovarian carcinomas." (PMID 37688374, 2023). "However, BMP7 protein expression and its potential clinical significance in ovarian carcinomas has been even less well studied." (PMID 37688374, 2023). "Previous transcriptomic data suggested that BMP7 expression may be disrupted in ovarian carcinoma and may play an important role in the aggressiveness of the disease." (PMID 37688374, 2023). "Similarly, in a recent study, knockdown of BMP7 in ovarian cancer cells A2780 cells inhibited migration and invasion." (PMID 37688374, 2023). "If not due to the evasion of therapy, the worse prognosis observed with high BMP7 expression in ovarian carcinomas may be due to the increased metastatic characteristics achieved during EMT, enabling rapid tumour progression." (PMID 37688374, 2023). "The relationship between BMP7 expression and overall survival in the current study suggests that BMP7 expression could potentially be used as a prognostic tool in ovarian cancer patients." (PMID 37688374, 2023). "However, the similarities between the two studies, with respect to patient survival strongly suggest that high BMP7 expression is of clinical importance in ovarian cancer patients." (PMID 37688374, 2023). "The lack of association between BMP7 expression and chemotherapy response in this study, may indicate that the aggressiveness BMP7 provides in ovarian cancer may be EMT‐related." (PMID 37688374, 2023).
ovarian carcinoma (continued). "The study provides evidence of the clinical importance of BMP7 in ovarian carcinomas." (PMID 37688374, 2023). "Furthermore, there is little known about BMP7 expression and its role in ovarian cancer." (PMID 37688374, 2023). "BMP7 expression could, however, be an independent prognostic tool in certain subtypes of ovarian carcinoma and thus, if numbers were increased, it would be useful to conduct future univariate and multivariate analyses within the different histological subtypes." (PMID 37688374, 2023). "Our group previously reported in vitro transcriptomic data that suggested that BMP7 protein may be important in the aggressiveness of ovarian cancer and, as a result, may possibly influence disease progression and overall survival of patients with ovarian cancer." (PMID 37688374, 2023). "For example, two separate studies in Ovarian cancer show copy number gains as frequent events, which we later determined to be due to amplifications in the BMP2 and BMP7 loci." (PMID 27114889, 2016).
pancreatic cancer (3 papers, 2016 to 2024). "Next, we sought to know if TGF-β1, a powerful promoter of EMT, and BMP-7, another member of the TGF-β superfamily of growth and differentiation factors and promoter of MET, impact EMT- and NED-associated gene expression in pancreatic tumor cells." (PMID 39682758, 2024).
renal cell carcinoma (3 papers, 2011 to 2024). "Only in renal cell carcinoma was BMP-7 expression significantly associated with better surgical outcome." (PMID 21224856, 2011).